EPCAM (epithelial cell adhesion molecule)
Diseases named in the same sentence as EPCAM in open-access papers (continued):
Sharing a sentence is not in itself a finding about the gene and the disease.
tumor (continued). "The assay discriminates tumor cells in the blood based on their expression of epithelial cell adhesion molecule (EpCAM)." (PMID 33917181, 2021). "The CellSearch system, which analyses CTCs by detecting epithelial cellular adhesion molecule (EpCAM) expression in individual tumours, was approved by the FDA as a CTC detection platform." (PMID 34034739, 2021). "EpCAM is generally overexpressed in carcinomas, and was found to be relevant for the detection of circulating tumor cells (CTC) and for cancer stemness." (PMID 34885075, 2021). "EpCAM-based cell surface markers for identification of epithelial cancers and as a target for circulating tumor cell (CTC) isolation and enrichment have long been established." (PMID 34054869, 2021). "We initially simulated delivery of a protein with a molecular weight of 70 kDa binding to the tumor marker EpCAM." (PMID 33921165, 2021). "In multicellular tumor spheroids, we observed strong binding-site barriers in combination with low apparent diffusion coefficients of 1 μm2·s−1 and 2 μm2 ·s−1 for EpCAM- and HER2-binding DARPin, respectively." (PMID 34070171, 2021). "The tumor cell population, defined as EpCAM+ strongly varied from 0.8% to 99.8% among the ascites samples, whereas the range of immune and mesenchymal‐like cells was between 2.3% to 95.8%, respectively." (PMID 34060699, 2021). "Of note, two patients with metastasis at diagnosis (high-grade RMS) showed detectable CTCs and were positive for EpCAM expression in tumor tissue." (PMID 34063272, 2021). "Binding between anti-EpCAM antibodies coated throughout the microfluidic channels and EpCAM molecules present on cell’s surface, while improving isolation purity, only occurs in part of the available CTCs, i.e., EpCAM-positive tumor cells." (PMID 33925308, 2021). "Induction of EpCAM expression occurs early in prostate carcinogenesis and the expression increases with Gleason score and tumor stage." (PMID 34298801, 2021). "The anti-EpCAM binding arm of Catumaxomab has been shown to bind EpCAM-positive tumor cells in vitro with high affinity and specificity." (PMID 34715784, 2021). "A total of 310 tumor fragments corresponding to 209 patients fulfilled the technical quality and TSR assessment criteria, including appropriate tissue quality, presence of tumor cells visible in four sides of the specimens, and informative EpCAM staining." (PMID 34834440, 2021). "In parallel, cells expressing high levels of EpCAM (epithelial cell adhesion molecule) while also expressing CD44 were also shown to enrich for tumor-initiating capabilities." (PMID 33671641, 2021). "While microCT analysis of Hif2α−/− PyMT+ mice did not reveal any differences in trabecular bone parameters, flow cytometric analysis of hindlimb bone marrow from Hif2α−/− PyMT+ mice revealed a significant reduction in the percentage of EpCAM+ tumor cells." (PMID 34556788, 2021). "Briefly, QDs were functionalized with anti-epithelial cell adhesion molecule (EpCAM) antibodies; EpCAM is highly expressed in tumor cells." (PMID 33802028, 2021). "The number of EpCAM-positive tumor cells ranged from 69 in an EC sample (before filtration (LDF)) to 263,076 in the Reservoir." (PMID 34715784, 2021). "An effective and easy-to-implement method for removing EpCAM positive tumor cells with metastasizing potential from blood collected during tumor surgery was invented based on the selectivity of the monoclonal anti-EpCAM antibody Catumaxomab." (PMID 34715784, 2021). "There was a significant decrease in the number of tumor cells (EpCAM+, PD-L1+) and M2 like macrophages (CD11b+CD64+CD206+ and CD11b+CD64+CD163+) with PD-L1 BiTE treatment, alongside a significant increase in activated T cells number (CD3+ and CD25+)." (PMID 33820820, 2021). "EpCAM (or CD326) is an epithelial cell marker that is frequently and most strongly expressed in tumor-associated antigens." (PMID 34575511, 2021).
tumor (continued). "Having confirmed EpCAM-positive tumor cells she was treated with six doses of catumaxomab starting with 20 μg up to 100 μg (total amount of antibody 470 μg)." (PMID 33837852, 2021). "We then analyzed the expression of immune checkpoint proteins, HLA-G, ILT-2, ILT-4, and PD-L1, using multicolor flow cytometry in EpCAM+-gated tumor cells from frozen CRC samples." (PMID 34054869, 2021). "A significant difference in the tumor bed-to-pre-existent mucosa expression ratio between biomarkers was found, with the lowest rank for EpCAM, followed by CEA, αvβ6, and uPAR (p < 0.01)." (PMID 33799475, 2021). "Epithelial cell adhesion molecule (EpCAM) is proposed to be an emerging biomarker for circulating tumor cells (CTCs) and is recognized as a novel target for adoptive T cell therapy." (PMID 33613769, 2021). "Distinct from other cells in circulation, CTCs express tumor proteins (e.g. cytokeratin (CK), epithelial cell adhesion molecule (EpCAM), and E-cadherin (ECAD) in epithelial malignancies) but lack leukocyte epitopes (e.g. CD45)." (PMID 34211050, 2021). "CAFs lack expression of lineage markers for epithelium and tumor cells, e.g., epithelial cell adhesion molecule (EpCAM), endothelium and lymphatics (e.g., CD31, LYVE1), and hematopoietic cells (e.g., CD45)." (PMID 33673197, 2021). "When assessing cell type interactions between CD8+ T cells (marker gene: CD8A) and tumor cells (marker gene: EpCAM), most of them showed interactions known to be mediating immunity, including that of CD155 with CD96 between CD8+ T cells and tumor cells." (PMID 34417435, 2021). "Co-immunostaining of CPT1 with tumor stem cell marker EpCAM in the culture spheroids showed that they are co-localized in the LCSCs." (PMID 34803493, 2021). "Recently, EpCAM on tumor-derived EV membrane was also employed as a promising tumor surface marker, while the tetraspanin family of proteins, such as CD63, CD9, and CD81, was mainly used as EV universal markers." (PMID 34900726, 2021). "An open-label, multicenter clinical study on the removal of EpCAM-positive tumor cells from blood collected during tumor surgery using the Catuvab device is initiated to validate these encouraging results." (PMID 34715784, 2021). "After being surface‐modified with the anti‐EpCAM Abs, specificity and sensitivity of the developed platform for isolating tumor cells were studied." (PMID 33898169, 2021). "Through in vivo experiments, we have determined that VCL can affect EMT and tumor immunity by regulating the expression of EPCAM." (PMID 33535187, 2021). "Confocal imaging showed CD90 and CD73 positive cells marking different mesenchymal cell populations surrounding epithelial cell adhesion molecule (EpCAM) positive tumour islands." (PMID 34740105, 2021). "A common strategy is EpCAM-dependent isolation, as is used in CellSearch, because epithelial tumor cells express EpCAM." (PMID 34025789, 2021). "Given the multifunctional role of EpCAM, modulation of EpCAM expression can have differential outcomes on tumor biology and EMT and EpCAM can either inhibit or promote EMT." (PMID 34209658, 2021). "Conversely, tumour EPCAM (HR=1.7, p=0.045), and CD95 (HR=4.9, p=0.046) were associated with poorer outcome." (PMID 35083152, 2021). "Herein, we described a novel immunotherapy strategy by directly targeting MUC-1 and EpCAM in tumor cells through the combination of EpCAM/CD3 BsAb and MUC-1/CD3 BsAb." (PMID 34522164, 2021). "Uptake by EpCAM+ tumor cells and other immune cells such as T cells and B cells was not detectable (data not shown)." (PMID 34683992, 2021). "The use of fluorescence-labeled contrast agents targeting CEA and EpCAM has been shown to be safe and feasible for tumor imaging in humans and is the subject of extensive investigation." (PMID 33799475, 2021). "In our study, tumor cells were stained with anti-EpCAM antibody (brown), which contrasted to EpCAM-negative stroma (blue)." (PMID 34834440, 2021).
tumor (continued). "Among five patients who progressed during tumor evolution, four were positive for tissue EpCAM expression and three had detectable CTCs at diagnosis." (PMID 34063272, 2021). "Overall, EpCAM is an appealing target, although its expression on healthy epithelia has limited the therapeutic window of systemic EpCAM-directed therapies due to on-target/off tumor side effects." (PMID 34829955, 2021). "In vitro studies showed that, after binding to EpCAM-positive tumor cells, MOC31PE is internalized and PE is able to block protein synthesis and to trigger apoptosis, rapidly inducing cell death." (PMID 34885075, 2021). "CellSearch® relies on the expression of the epithelial cell adhesion molecule (EpCAM) for the quantification of CTCs in different tumor types." (PMID 34829387, 2021). "In the present study, an ultrasensitive electrochemical cytosensor for specific capture, quantitative detection, and noninvasive release of EpCAM-positive tumor cells was developed." (PMID 34858966, 2021). "The amount of precipitated EpCAM positive EVs in tumor patient plasma was more than that from healthy controls." (PMID 34439276, 2021). "In this study, a H3K4me3-marked signal was found at the EPCAM promoter and positively correlated with high RNA-Seq expression in the tumor samples." (PMID 33916417, 2021). "Consistently, images of immunofluorescence staining showed EpCAM+CD45high cells within primary tumor tissues from CRC patients, while they were rarely detected in matched normal colorectal tissues." (PMID 34522210, 2021). "An increase in EpCAM expression was found in tumor tissues of OC patients after platinum-based chemotherapy, which suggests the potential use of EpCAM-targeted therapy as a second-line treatment." (PMID 34439094, 2021). "A total of 1505 individual gene copy numbers were measured (copy number > 0/μL) from 131 EpCAM-positive cells most probably of tumor origin." (PMID 34590615, 2021). "The tumor compartment, identified as Cluster-7 is characterized by high expression of EpCAM, MUC1, E-Cadherin and CA125, and low expression of pan-leucocyte marker CD45." (PMID 33135052, 2021). "Ec1-LoPE has specific binding to tumors and provides an anti-tumor effect in EpCAM-expressing SKOV3 xenografts." (PMID 34439094, 2021). "The functional impact of EpCAM expression on tumor biology is frequently dependent on the cancer type and predominant oncogenic signaling pathways, suggesting that the role of EpCAM in tumor biology and EMT is multifunctional." (PMID 34209658, 2021). "A wire modified by an EpCAM antibody is placed into the vein of the arm for 30 min, and then the tumor cells on the steel wire are identified under a fluorescence microscope for early cancer diagnosis." (PMID 34798902, 2021). "It has been proven that EpCAM expression can be acquired during tumor progression and is highly expressed in cancer stem cells." (PMID 34063272, 2021). "Recent studies had shown that the important markers of EMT, namely vimentin, E-cadherin, FSP1 and EPCAM, that can effectively help us find tumor cells undergoing the EMT process." (PMID 33535187, 2021). "Here, the AD populations included a high percentage of tumor cells, as they showed a strong staining for EpCAM." (PMID 34060699, 2021). "Among the tumor cell clusters identified, two separately clustered categories of cells were observed: tumor cells expressing EpCAM, FOLR1, or both, with high expression of CD47 and those without high expression of CD47 (total clusters n = 10)." (PMID 33670410, 2021). "This was demonstrated for patient 2 who received a second treatment cycle and thereafter showed a complete elimination of EpCAM-positive tumor cells in the urine." (PMID 33837852, 2021). "Exosomes had previously been isolated using ultracentrifugation and immunoaffinity magnetic beads with anti-epithelial cell adhesion molecule (EpCAM), which was used as a marker for tumor-derived exosomes." (PMID 33801442, 2021).
tumor (continued). "The dMMR sample harbored low-frequency instability, as revealed by MSI PCR, and a possible EPCAM deletion in the tumor, as observed from next-generation sequencing." (PMID 33747906, 2021). "EpCAM expression is progressively lost with tumor dedifferentiation in poorly differentiated (PDTC) and anaplastic thyroid (ATC) cancers." (PMID 34209658, 2021). "All critical steps are described that required in situ addition of the immuno-affinity feature to hemodialyzer cartridges in order to capture EpCAM positive circulating tumor cells, which represents ~80% of cancer cell types." (PMID 34443432, 2021). "For Hep3B inoculation, EpCAM-High group has shown significantly higher tumor growth compared with EpCAM-Low (p < 0.005)." (PMID 32547703, 2020). "Epithelial cells were sorted for epithelial cell adhesion molecule (EpCAM), which is exclusively displayed in epithelia and epithelial‐derived neoplasms and expressed in various carcinomas, including EAC." (PMID 32255255, 2020). "A number of CAR-modified NK-92 or NK-92MI cells have been constructed toward a panel of tumor-associated antigens, including ErbB2, CD4, CD19, CD20, CD33, CD38, CD138, GD2, and epithelial cell adhesion molecule (EPCAM)." (PMID 32848731, 2020). "CAR T-cells targeting EpCAM have been shown to significantly block tumor growth in xenografts and to secrete cytotoxic cytokines, including interferon-γ (IFN-γ) and tumor necrosis factor alpha (TNF-α) in vitro." (PMID 32849491, 2020). "Recently, the CellSearch® system (an EpCAM-dependent method) was also applied for the enumeration of EpCAM+ large tumor-derived EVs (tdEVs)." (PMID 32764280, 2020). "After incubation with IL-6, the total concentration of the EpCam+CD44hiCD24– and EpCam+CD44hiCD24low cells decreased, and the concentration of the EpCam+CD44lowCD24– tumor cells drastically increased (2.3 times), i." (PMID 32523653, 2020). "The conventional CTCs positive sorting method mainly involves a positive enrichment method designed on the basis of high expression markers on the surface of tumor cells such as EpCAM labeled on the surface of immunomagnetic spheres or microfluidic chips." (PMID 33208163, 2020). "Taken together, we demonstrated that EpCAM+ Hepa1-6 CSCs possess predominant tumor-initiating properties in the NASH microenvironment of immunocompetent mice." (PMID 32547703, 2020). "Here, we have systemically investigated the role of EpCAM+ cancer cells in tumor initiation in orthotopic HCC models." (PMID 32547703, 2020). "We observed that tumor implants were much less and smaller in mice receiving EpCAM-siPKCι aptamer than those seen in mice administered with Control aptamer." (PMID 32820156, 2020). "Extending the scope of the study, we also showed that the cell fate instated by EpCAM overexpression can significantly impact in vivo tumor growth, RT treatment efficacy, and, most importantly, increased metastasis to the distant critical organ." (PMID 33490064, 2020). "Expression of anti-ROR1 CAR was induced only upon engagement of EpCAM or B7-H3 to the syNotch receptor, thus only dual positive tumour cells were eliminated, and on-target off-tumour toxicities were prevented." (PMID 32824734, 2020). "In summary, homogeneous EpCAM-expression was significantly indicative for higher local aggressiveness and earlier tumor dissemination compared to heterogeneous EpCAM-expression." (PMID 33225916, 2020). "Fluorescence-labeled anti-EpCAM antibodies allow the detection of residual tumor nodules in the millimeter size range using intraoperative imaging systems." (PMID 32507912, 2020). "Zhang’s group developed a microfluidic chip-based CTC capture system in which anti-EpCAM modified Fe3O4 MNPs’ array inside a microchannel was utilized to identify and separate tumor cells from a whole blood sample." (PMID 32823926, 2020).
tumor (continued). "The trifunctional mAb catumaxomab targets CD3 on T-cells, Fc-receptors on innate immune cells, and EpCAM on tumor cells, and it is heterogeneously overexpressed in epithelial cancers, including EOC." (PMID 33260974, 2020). "Both morphological criteria and positivity for EPCAM strongly suggest that these cells are tumor cells." (PMID 32533757, 2020). "On the other hand, EpCAM‐based methods detected CTCs on a series of tumor‐specific epithelial markers, which contributed to the high specificity." (PMID 32628360, 2020). "The CELLSEARCH® CXC kit was used to detect circulating tumor cells (CTCs) based on the expression of epithelial cell adhesion molecule (EpCAM)." (PMID 32021935, 2020). "As expected, we found that CD44+/CD24−/low/EpCam+ MDA-MB-468 cells had higher tumor-initiating ability in this model." (PMID 32183150, 2020). "Further studies investigating the transcriptional characterization of EpCAM-expressing tumor cells are required." (PMID 33225916, 2020). "A modified antibody–cytokine conjugate, anti-EpCAM-IL-2, was used to bind to the epithelial cell adhesion molecule (EpCAM) protein expressed on the surface of the tumor cells." (PMID 32932680, 2020). "In summary, EMT emerged as a transient state with gradual changes, which strongly contributes to tumor progression and which can be monitored using a panel of dominant markers including EpCAM." (PMID 32507912, 2020). "The interaction of E-cadherin, integrin αvβ6 and EpCAM on cancer cells can trigger the activation of tumor-mediated fibroblasts that then influence gene expression and sensitivity to therapeutic agents." (PMID 32764280, 2020). "During the cancer development the expression pattern of EpCAM change from basal and basolateral membrane in normal epithelial to the apical surface in tumor epithelial cells." (PMID 32383027, 2020). "The authors correlated the type of neoplasm with the size and location of the deleted region in the EPCAM gene." (PMID 33003511, 2020). "For diagnosis application, EpCAM is used as a specific membrane biomarker for antibody-based isolation of circulating tumor cells from mCRPC patients." (PMID 32183880, 2020). "High CAIX expression was detected in tumor-initiating cells (TICs) positive for pancreatic cancer stem cell markers EpCAM+/CD44+/CD24+, isolated from PDAC patient samples." (PMID 32707920, 2020). "We identified five classes of tumor cells (C8, C9, C10, C18, C20), which expressed the tumor cell marker genes EPCAM, CEACAM6, or MKI67." (PMID 32580738, 2020). "Again, all dormant tumor cells that grew in culture from the lungs showed comparable levels of expression of neu or EpCAM and were predominated by the CD24+CD44+ fraction." (PMID 33115528, 2020). "Hep3B/Nu-J experiments provide glimpses into the nature of EpCAM-expressing CSCs that hierarchal EpCAM expression bears different tumor initiating capability." (PMID 32547703, 2020). "EpCAM represents a marker for the epithelial status of primary and systemic tumor cells and emerges as a measure for the metastatic capacity of CTCs." (PMID 32507912, 2020). "Primary cultures of EpCam+ tumor cells from patients with stemness gene amplifications revealed high proliferative activity." (PMID 32523653, 2020). "Calretinin‐positive cells were identified as tumor cells based on their morphology and expression of the carcinoma cell marker EPCAM." (PMID 32533757, 2020). "In line with published data, tumor cells clustered with their matched EPCAM + LN cells, suggesting that tumor cell transcriptomes vary more between patients than between PTs and LNs." (PMID 31964880, 2020). "In each case, the tumor spectrum is different and varies in relation to the size and location of the EPCAM 3′-end deleted fragment." (PMID 33003511, 2020). "In this study, we demonstrated with immunohistochemistry that EpCAM is a suitable cell-surface protein that can be used as a promising target for tumor-targeted molecular imaging in EOC." (PMID 32545676, 2020).